MIR222HG (miR222/221 cluster host gene)
Synonyms: Lnc-Ang362; formerly LINC02595
Gene: Long non-coding RNA gene on chromosome X (45,745,210 to 45,851,873, reverse strand). Ensembl gene ENSG00000270069.
Gene Ontology:
Cellular component: RISC complex
Diseases named in the same sentence as MIR222HG in open-access papers:
MIR222HG is named in the same sentence as 6 diseases in open-access papers, as found by Europe PMC text mining. Sharing a sentence is not in itself a finding about the gene and the disease. The quoted sentences say what the papers report.
prostate carcinoma (2 papers, 2023). A carcinoma that arises from epithelial cells of the prostate gland. "miR-221/222 and the host gene MIR222HG, have been reported to regulate prostate cancer, atherosclerosis and hypertension, pulmonary arterial hypertension, and cell cycle re-entry." (PMID 37205104, 2023). "In tumors, MIR222HG has been reported to promote the development of prostate cancer." (PMID 37351164, 2023).
asthma (1 paper, 2023). "In this study, we screened key asthma-related genes (LUCAT1, MIR222HG, CD300E, and IER2) and immune cell infiltration profiles through bioinformatic analysis, which could provide insights into the pathogenesis of asthma and new perspectives and approaches for asthma diagnosis and treatment." (PMID 37259023, 2023).
MIR222HG also shares sentences with these, for which no sentence is quoted: tumor (2 papers); atherosclerosis (1); Hypertension (1); pulmonary arterial hypertension (1).